TRPV1 (transient receptor potential cation channel subfamily V member 1)
Diseases named in the same sentence as TRPV1 in open-access papers (continued):
Sharing a sentence is not in itself a finding about the gene and the disease.
colitis (continued). "Another independent study also showed that chemogenetic inhibition or pharmacological ablation of Trpv1+ neurons exacerbates DSS-induced colitis through dysregulation of the gut microbiota." (PMID 37336989, 2023). "It is intriguing that although both TRPV1 and TRPA1 mediate Ca2+ influx that initiates intracellular Ca2+ signaling in a similar manner, loss of function of TRPV1 and TRPA1 show opposite phenotypes in mouse models of experimental colitis." (PMID 36459135, 2023). "We found that, as previously reported in wild type C57BL/6J mice, TRPV1-hM4Di colitis mice exhibited VHS at 45 and 60 mmHg distension pressures compared with control." (PMID 34954381, 2022). "Overall, our work provides a causal relationship between TRPV1+ visceral afferent activity, microglial response, and VHS in colitis." (PMID 34954381, 2022). "Given the importance of TRPA1 and TRPV1 nociceptive sensory neurons in colitis-mediated nociception, the targeted inhibition of these nociceptors can be a promising therapeutic strategy for alleviation of IBD-associated pain." (PMID 36076974, 2022). "Inhibition of TRPV1 in T cells by genetic factors or drugs led to reduction of the symptoms of colitis." (PMID 35634308, 2022). "As it relates to the colon, in animals with DSS‐induced colitis, only the expression of TRPV1 and Ramp1, on experimental Day 35, was affected, with a significant up‐regulation (both p < 0.05 vs. control)." (PMID 36239298, 2022). "In the T-cell-mediated colitis model, TRPV1 was shown to promote T cell and intestinal inflammatory responses." (PMID 35634308, 2022). "In the present study, we showed that TRPV1-expressing visceral afferents control microglial reactivity in colitis-induced VHS." (PMID 34954381, 2022). "Overall, our work shows that TRPV1+ nociceptor-microglia interactions can precipitate the establishment of persistent visceral pain following colitis, through a central mechanism involving microglial P2RY12." (PMID 34954381, 2022). "Using the DSS model of experimental colitis, we previously found that released microglial granulocyte-colony stimulating factor sensitizes TRPV1+ visceral nociceptors that converge onto the spinal dorsal horn." (PMID 34954381, 2022). "We next determined the mechanism by which TRPV1+ neurons promote microglia activation in response to neuronal activity or experimental DSS colitis." (PMID 34954381, 2022). "We found that chemogenetic inhibition of TRPV1+ neurons reduced colitis-induced microglia activation and VHS, whereas chemogenetic activation without colitis, was sufficient to enhance microglial reactivity leading to VHS." (PMID 34954381, 2022). "Genetic approaches were used to define the role of TRPV1 and analyze the effects of dinitrobenzene sulfonic acid (DNBS)-induced colitis in TRPV1-deficient (TRPV1-/-) mice." (PMID 35003109, 2021). "Akt activity (phosphorylation) is increased in colonic afferent cells in a colitis state and is coexpressed with TRPV1 and TrkA." (PMID 34646326, 2021). "Immunofluorescence analysis revealed a significant increase in S100β (102.11% vs. vehicle) and TRPV1 (+89.45% vs. vehicle) in the DRG of DNBS-treated rats compared to the vehicle group on day 7 after colitis induction (p < 0.0001)." (PMID 34829900, 2021). "In T-cell-transfer colitis model, the activation of TRPV1 tended to exacerbate the intestinal inflammation, while the colitis was less severe when the TRPV1 in T cell was genetically or pharmacologically inhibited." (PMID 32153564, 2020). "It was further revealed that the severity of TNBS-induced colitis in the TRPV1+ fibers-denervated rats was drastically increased within 3–7 days after TNBS administration." (PMID 32153564, 2020). "SP was demonstrated to enhance the sensitivity and function of TRPV1 in DSS-induced colitis and in vitro, suggesting the engagement of neuropeptides in VHS." (PMID 32153564, 2020). "Noteworthy, several publications have reported the protective effects of TRPV1 in experimental colitis." (PMID 32153564, 2020).
colitis (continued). "A protective role of TRPV1 was also identified in oxazolone-induced mice colitis, iodoacetamide-induced rat acute colitis, and formalin-induced rabbit acute colitis." (PMID 32153564, 2020). "For example, both TRPV1 agonists and antagonists were shown to protect against experimental colitis." (PMID 33251043, 2020). "In DSS-treated rats, a daily administration of capsaicin was able to reduce the severity of colitis, while a desensitization of TRPV1+-fibers dramatically worsened the inflammation." (PMID 32153564, 2020). "In a spontaneous IL10−/− colitis model both genetic deletion and pharmacologic inhibition of TRPV1 resulted in attenuated inflammation." (PMID 30935063, 2019). "TNBS induces similar severe acute colitis in wildtype and Trpv1−/−, but reduced inflammation in Trpa1−/− mice or wildtype animals treated with the TRPA1 antagonist HC-030031." (PMID 30935063, 2019). "Meanwhile, Massa and co-workers found more severe DNBS-induced colitis in Trpv1−/− mice, suggesting a protective role of TRPV1." (PMID 30935063, 2019). "They provided clear experimental evidence in a T cell adoptive transfer model that TRPV1-expressing CD4+ T cells are involved in colitis pathogenesis." (PMID 30935063, 2019). "Special emphasis was focused on the role of TRPV1 that has been examined in vivo in models of T cell-mediated colitis via its pro-inflammatory properties and regulation of cytokine production." (PMID 30274279, 2018). "It was also demonstrated that icilin, a specific TRPM8 agonist, attenuates TRPV1-dependent calcitonin gene-related peptide release in the colon and is suggested as a promising therapeutic target for the treatment of colitis." (PMID 30298050, 2018). "In this regard, it has been shown that genetic deletion or pharmacological inhibition of TRPV1 in CD4+ T cells substantially reduced colitis severity in animal models of human inflammatory bowel disease." (PMID 30274279, 2018). "Administration of TRPM8 agonists in the colitis models inhibited TRPV1-dependent CGRP expression, reduced pro-inflammatory cytokines, and attenuated the common hallmarks of colitis such as bowel thickness and infiltration of granulocytes." (PMID 30087301, 2018). "If TRPV1 defunctionalization protects the human colon from C. difficile toxin A colitis as it does in rats as shown here, this suggests a possible new therapy for the human disease caused by C. difficile." (PMID 28484490, 2017). "Icilin attenuates TRPV1-dependent calcitonin gene-related peptide release in the colon and is a promising therapeutic target for the treatment of colitis." (PMID 28861042, 2017). "It has been assumed that inhibition of TRPV1 in peptidergic colonic sensory neurons by CPZ attenuates colitis through reducing neuropeptide release and neurogenic inflammation." (PMID 27356469, 2016). "A mouse post-inflammatory chronic hypersensitivity model using intracolonic trinitrobenzene sulphonic acid (TNBS), which induces colitis, also showed TRPV1 as an important mediator of mechanical and chemical visceral hyperalgesia." (PMID 27322240, 2016). "The in vivo observation that CPZ enemas effectively inhibited colitis in TRPV1 null mutant mice imposed the question on TRPV1-independent neuronal effects of CPZ." (PMID 27356469, 2016). "The current results provide three lines of evidence supporting the concept that a neurogenic mechanism involving TRPV1 activation plays a role in nicotinic inhibition of colitis." (PMID 26881175, 2016). "In a rat model of dextran sulfate sodium (DSS) colitis, neonatal animals chemically deprived of TRPV1-expressing fibers by treatment with capsaicin, as well as those given a TRPV1 antagonist (JNJ 10185734) were both protected from the damaging effects of DSS." (PMID 27322240, 2016). "Our first goal was to determine if TRPV1 activation plays a role in toxin A-induced colitis as it does in toxin A-induced ileitis in rats." (PMID 25045574, 2014).
colitis (continued). "Inhibition of 5-LO by 5-ASA disrupts this pathway and supports the concept that LTB4 activation of TRPV1 plays a role in toxin A colitis." (PMID 25045574, 2014). "Our recent study in a colitis-induced visceral pain model shows that BDNF is largely co-expressed with the transient receptor potential cation channel TRPV1, suggesting a role of BDNF in nociception." (PMID 24303055, 2013). "Taken together, these results suggest that the effects of colitis-induced cross-sensitization on bladder function were attenuated in TRPV1−/− mice." (PMID 23305398, 2013). "Our behavioral results established that the development of abdominal hypersensitivity induced by colitis upon mechanical stimulation of the lower pelvic region was delayed in TRPV1−/− mice." (PMID 23305398, 2013). "To examine the phenotype of BDNF immunoreactive neurons in the DRG in order to validate a role of BDNF in sensory plasticity, we performed double immunostaining of BDNF and the nociceptive marker TRPV1 in the L1 DRG at 3 days of colitis." (PMID 22335898, 2012). "Apart from protecting the GI mucosa, TRPV1 activation has been found to exacerbate inflammation and injury in certain models of ileitis, colitis and pancreatitis." (PMID 21420431, 2011). "In a rat model of DSS colitis, neonatal animals chemically denervated of TRPV1 fibres by treatment with capsaicin, and those given a TRPV1 antagonist in established DSS colitis, were both protected from the damaging effects of DSS." (PMID 18252749, 2008). "Additionally, the substantial proportion of Il17ra‐positive sensory neurons co‐expressing Trpv1 further supports a pronociceptive role for IL‐17 in colitis." (PMID 40827457, 2025). "TRPV1 is abundantly expressed in immune cells, including resident colonic immune cells, particularly CD4+T cells, and has been implicated in the underlying pathogenesis of T cell-mediated murine colitis." (PMID 40560060, 2025). "Additionally, in colitis-associated colon cancer, stimulation of TRPA1, TRPM2, and TRPV1 increases mitochondrial ROS and Zn2+ dysregulation, promoting apoptotic cell death, an effect mitigated by antioxidant treatment with Sambucus ebulus L." (PMID 40813985, 2025). "This suggests an increased TRPV1 function and susceptibility of mice to DSS-induced colitis." (PMID 38731999, 2024). "Genetic ablation of TRPV1 or TRPA1 significantly attenuates the severity of colitis." (PMID 36459135, 2023). "TRPV1 was upregulated in acute human inflammatory bowel diseases and experimental colitis." (PMID 37269788, 2023). "Given the pro-nociceptive effects of TRPV1, its downregulation during acute colitis might be interpreted as a compensatory mechanism developed during acute inflammation to avoid abnormal excessive pain." (PMID 37893131, 2023). "Furthermore, the severity of colitis was positively correlated with the gradient of TRPV1 positive neurons in the colon." (PMID 35646918, 2022). "Similarly, TRPV1 antagonism has also been proven to attenuate disease severity in mouse and rat models for colitis." (PMID 36076974, 2022). "As activation of spinal microglia is a cellular surrogate of VHS in colitis, we determined whether inhibition of TRPV1+ visceral afferents was sufficient to prevent microglial activation in the spinal cord." (PMID 34954381, 2022). "Chronic CNO treatment normalized the VHS in TRPV1-hM4Di colitis mice." (PMID 34954381, 2022). "The rather ambiguous findings concerning the roles of TRPV1 in colitis required further scrutiny." (PMID 32153564, 2020). "In experimental colitis models, TRPV1 expression was also found to be altered." (PMID 32153564, 2020). "In Trpv1−/− mice, the DSS-induced colitis was less severe, and a DSS-associated upregulation of SP-positive fibers was reduced, demonstrating a crosstalk between TRPV1 and neurogenic inflammation in colitis." (PMID 32153564, 2020). "Meanwhile, a TRPV1 antagonist suppressed colitis and colorectal distension in animal models." (PMID 32823895, 2020).
colitis (continued). "Visceral hyperalgesia and increased visceromotor response (VMR) were also confirmed in rats with 2,4,6-trinitrobenzenesulfonic acid (TNBS)-induced colitis, while TRPV1 antagonist (JYL1421) could prevent and relieve the VHS." (PMID 32153564, 2020). "We therefore hypothesized that epithelial TRPV1 overactivation mediated the deleterious effects during colitis." (PMID 33251043, 2020). "Goso and co-workers provided the first evidence for a protective role of TRPV1-expressing peptidergic sensory nerves via the release of the protective neurotransmitter CGRP upon acute co-administration of capsaicin in a TNBS-induced colitis model." (PMID 30935063, 2019). "On the other hand, TNBS-induced colitis animal model has shown that TRPV1 may have a protective role in the inflammatory process due to TRPV1 −/− knockout mice, revealing low inflammation activity index and myeloperoxidase activity level." (PMID 30150894, 2018). "It has been revealed that TRPM8 activation leads to a decline in TRPV1 activity, which may be of therapeutic benefit in clinical circumstances such as treatment of TRPV1-mediated inflammatory hyperalgesia, colitis, and dry eye syndrome." (PMID 28861042, 2017). "TRPV1 desensitization in DSS-treated rats not only suppresses ongoing activity in spinal afferent neurons but also prevents the development of anxiety- and depression-like behavior associated with DSS-induced colitis." (PMID 29213271, 2017). "In order to determine if TRPV1 mediates a portion of toxin A-induced colitis as it does ileitis, colonic segments were pretreated for 30 minutes with intraluminal administration of a TRPV1-defunctionalizing concentration of the TRPV1 partial agonist, I-RTX, before toxin A injection." (PMID 25045574, 2014). "Additionally, support for the involvement of TRPV1 in chronic colitis comes from animal studies of TNBS colitis, dextran sulfate-induced colitis, and colitis caused by adoptive transfer of CD4+/CD25− T cells in SCID mice." (PMID 25045574, 2014). "Therefore, we first sought to determine if pharmacological antagonism of TRPV1 inhibits toxin A colitis as it does toxin A ileitis in rats." (PMID 25045574, 2014). "Our results provide direct evidence that the lack of TRPV1 receptors does not prevent the occurrence of colon-bladder cross-sensitization induced by transient colitis, however, several important physiological characteristics of bladder function are altered by the knockout of TRPV1 gene." (PMID 23305398, 2013). "However, in TRPV1−/− neurons, acute colitis induced a rightward shift in steady-state inactivation by 7 mV (V1/2 = −39.7 ± 1.9 mV in the vehicle group vs −32.7 ± 1.7 mV in TNBS group, P ≤0.05)." (PMID 23305398, 2013). "Likewise, bladder capacity was reduced by 64% in WT mice and by 37% in TRPV1−/− littermates during colitis (P ≤0.05 to vehicle)." (PMID 23305398, 2013). "Experimental colitis in the mouse is attenuated by TRPV1 antagonism or knockout." (PMID 21420431, 2011). "However, diametrically opposed to these observations there are also reports of TRPV1 having a protective role in inflammatory models, with TRPV1 activation improving DSS-induced colitis in mice." (PMID 27713376, 2010). "Similarly, in rats and mice TRPV1 antagonists attenuate disease severity in dextran sulphate sodium (DSS)-induced colitis." (PMID 27713376, 2010). "This plasticity of TRPV1 expression may be a more general feature of chronic pain signals since a recent study found that during colitis TRPV1 protein levels were significantly increased by nerve growth factor (NGF) in specific rat colonic afferent neurons of both L1 and S1 DRG neurons." (PMID 38919332, 2024). "Chronic CNO treatment did not affect colitis-induced body weight loss, macroscopic damages, cytokine production in TRPV1-hM4Di, or hM4Di littermate controls, indicating that inhibition of TRPV1 visceral afferents was not sufficient to reduce the severity of colitis." (PMID 34954381, 2022).
colitis (continued). "Thus, we speculated that TRPV1 gain of function exacerbates DSS-induced colitis, at least in part, through promoting NFATc2 activation in DCs." (PMID 33251043, 2020). "However, the reported role of TRPV1 in colitis development is sometimes contradictory." (PMID 33251043, 2020). "Thus, colonic epithelial cells are not the primary targets for TRPV1 hyperactivation to confer enhanced susceptibility to colitis." (PMID 33251043, 2020). "Therefore, it can be hypothesized that the excitatory mechanism modulated by TRPV1 mainly particulate during early stage of experimental colitis." (PMID 32153564, 2020). "However, pretreatment with 5-ASA did not protect against direct TRPV1-mediated colitis caused by capsaicin." (PMID 25045574, 2014). "Thus, toxin A stimulates colonic LTB4 resulting in activation of TRPV1, release of SP, and colitis." (PMID 25045574, 2014). "However, the modulatory effects of PKC and ROK pathways could be associated with indirect mechanisms such as the altered release of sensory neuropeptides from TRPV1 fibers triggered by colonic inflammation." (PMID 23305398, 2013). "However, TRPV1−/− mice had prolonged intermicturition interval and increased number of non-voiding contractions at baseline followed by reduced urodynamic responses during active colitis." (PMID 23305398, 2013). "The search terms used were "Transient Receptor Potential Channels", "TRP channels", "TRPV1", "TRPA1", "TRPV4", "TRPV2", "TRPM2", "TRPM3", "TRPM7", "TRPM8", "TRPC3", "colitis", "inflammatory bowel disease", "IBD", "ulcerative colitis", "Crohn Disease"." (PMID 41096659, 2025). "Novel anti-inflammatory effects of TRPV1 in LPS-induced sepsis are also highlighted, wherein human models of TNBS- and DSS-induced colitis and IBD report predominantly pro-inflammatory characteristics of this channel." (PMID 38731999, 2024). "Intraperitoneal and intrathecal administration of TRPV1 and TRPA1 antagonists exerts analgesic effects in a rat colitis model that emphasizes central nervous system mechanisms (Ref." (PMID 38659380, 2024). "Our results demonstrated that DSS colitis upregulated SP, HA, BK, PGI2, and 5-HT expression in the skin and increased TRPV1, TRPA1, and TH in L6 DRG, implying that DSS promoted surface neurogenic inflammation evoked by sympathetic-sensory coupling in skin-DRG." (PMID 36910013, 2023). "In conclusion, EA at Zusanli (ST36) relieved hyperalgesia induced by colitis via the inhibition of surface neurogenic inflammation and sympathetic sprouting into the DRG, which were mediated by TRPV1/CGRP, ERK, and TLR4 signaling pathway deactivation." (PMID 36910013, 2023). "Mechanically, EA treatment reduced the activation of the TRPV1/CGRP, ERK, and TLR4 signaling pathways in L6 DRG of colitis rats." (PMID 36910013, 2023). "A previous report indicated that the blockade of receptor channels such as TRPV1 and TRPA1 on nociceptive sensory neurons was shown to attenuate experimental colitis by suppressing the release of GRP and SP." (PMID 36910013, 2023). "Here, we report that selective activation of TRPV1+ visceral neurons is sufficient to drive P2RY12 expression in the spinal cord, as found in DSS colitis." (PMID 34954381, 2022). "In the course of colitis, the expression of TLR4 in DRG is increased, which upregulates TRPV1 expression and TRPV1 current density, mediates inflammatory pain, and regulates inflammatory state." (PMID 35646918, 2022). "Colitis rats supplemented with 12 mg CAP/kg bw for 4 weeks decrease serum IL-6 levels and protein expression of TRPV1 and TRPA1 in the colon, and increase serum SOD and CAT activities and colonic IL-10 levels." (PMID 35269566, 2022). "Multiple pieces of evidence have confirmed the pro-inflammatory role of TRPV1+ and TRPA1+ neurons in experimental colitis." (PMID 35646918, 2022).